HOXC8 (homeobox C8)
Diseases named in the same sentence as HOXC8 in open-access papers (continued):
Sharing a sentence is not in itself a finding about the gene and the disease.
tumor (31 papers, 2009 to 2026). "Further evidence from this cancer, confirmed that enhanced expression levels of HoxC8 correlated with loss of differentiation suggesting a role for this Hox protein in tumour invasion and metastasis." (PMID 41535654, 2026). "To ensure that deterred tumor development was linked to pyroptosis led by the reduction of HOXC8, we performed immunohistochemistry to analyze the abundance of HOXC8, caspase-1, Ki67 and cleaved caspase-3 in tumors excised from Chol-NC and Chol-siHOXC8 groups." (PMID 40701951, 2025). "After evaluating the genetic alteration of the HOXC family, we focused on HOXC8 and its upregulation was associated with the tumor grade in patients with STAD." (PMID 37670969, 2023). "In this study, the HOXC family was evaluated in patients with STAD, and HOXC8 expression was upregulated in STAD tumor tissues and associated with worse overall survival." (PMID 37670969, 2023). "Nevertheless, co-overexpression of sh-HOXC8 together with HOXC-AS3 suppressed the increase in tumour volume and weight caused by HOXC-AS3 overexpression." (PMID 35387975, 2022). "For example, HOXC8 expression is selectively turned on in human cervix cancer cells and is associated with the loss of tumor differentiation in human prostate cancer cells." (PMID 24810778, 2014). "Remarkably, an inverse relation was found between tumour grade and expression level of Hoxc8 mRNA, indicating that the loss in HOCX8 mRNA expression is related to tumour progression." (PMID 21712827, 2011). "In line with this, the expression of HOXC8 protein in PDAC tissues was inversely associated with both tumour grade and liver metastasis." (PMID 21712827, 2011). "According to the clinical data, we found that HOXC8 expression was associated with tumor size." (PMID 37670969, 2023). "The data showed that HOXC8 expression was significantly associated with tumor stage (P=0.044)." (PMID 37670969, 2023). "High expression of HOXC8 was associated with the tumor grades in STAD patients." (PMID 37670969, 2023). "Another possibility could be that HOXC8 up-regulation is associated with tumour cell dissemination from the primary, a function that is dispensable at later, metastasised stages." (PMID 21712827, 2011). "With limited number of athymic nude mice, we showed that lipid-conjugated HOXC8 siRNA deterred tumor development." (PMID 40701951, 2025). "The ability of HOXC8 shRNAs to potently induce pyroptosis led us to investigate their effect on tumor development of LUAD cells." (PMID 40701951, 2025). "IHC of tumor sections from mice receiving HOXC8 siRNA displayed strong caspase-1 but reduced Ki67 staining without alteration of cleaved caspase-3 levels, indicating that tumor suppression was due to pyroptosis." (PMID 40701951, 2025). "Using RNA-seq data from 498 NB tumor samples, we observed that low expression of HOXC8 and HOXC9 correlates with poor survival, and this is consistent with an earlier report." (PMID 39528654, 2024). "High levels of HOXC8 mRNA expression also correlated with tumor stats, indicating that HOXC8 plays a role in STAD progression." (PMID 37670969, 2023). "Using HPA028911 antibody labeling, it was found that HOXC8 was not stained in normal alveolar tissue, but moderately stained in alveolar macrophages, and HOXC8 was moderately stained in LUAD tumor tissue." (PMID 36650426, 2023). "Knockdown of HOXC8 robustly suppressed tumour growth with significantly reduced tumour volume and weight compared to the control group." (PMID 35387975, 2022). "HOXC8 is localised in the cytoplasmic of tumour cells, and MS4A2 is expressed in interstitial cells." (PMID 33557848, 2021). "Altered HOXC8 levels have been documented in a variety of tumor types, and have been shown to be of biological and prognostic significance." (PMID 32366326, 2020). "LncRNA HOTAIR and HOXC8 have been highlighted in existing literature as factors involved in tumour formation." (PMID 31389660, 2019).
tumor (continued). "Consistent with our analysis findings, the mean expression levels of SLC43A1 and ELOVL6 were significantly lower while HOXC8 was significantly higher in CCA samples than in non-tumor liver samples in the GSE26566 dataset." (PMID 31448221, 2019). "Taken together, our study shows that homeobox genes represent novel biomarkers of breast CSC and that HOXC8 functions as a novel tumour suppressor gene by regulating breast CSC proliferation and differentiation." (PMID 28202042, 2017). "HOXC8 was consistently downregulated in stem/progenitor cells of all breast molecular subtypes, thus representing an interesting tumour suppressor candidate." (PMID 28202042, 2017). "Of the altered genes, HOXC8 demonstrated to function as a possible novel tumour suppressor in breast CSC by regulating stem cell self-renewal, differentiation and transformation." (PMID 28202042, 2017). "In primary and metastatic tumour samples, immunohistochemistry staining for HOXC8 was always stronger in surrounding than in neoplastic tissues." (PMID 21712827, 2011). "This assumption is in line with our subsequent functional analysis showing increased proliferation, colony formation and migration of tumour cells after Hoxc8-mRNA down-regulation." (PMID 21712827, 2011). "Further support for the assumption that HOXC8 has a defensive role against tumour cell growth is derived from the fact that this transcription factor regulates proteins, such as OPN and ON, which are involved in cancer progression." (PMID 21712827, 2011). "Likewise, in ovarian epithelial carcinoma, elevated levels of HoxC8 was reported in tumour samples with poor prognosis." (PMID 41535654, 2026). "Given the spatiotemporal expression of HOXC8, it may also act as a tumor suppressor depending on the organ involved." (PMID 40701951, 2025). "From the perspective of data mining, this study suggests that MMP12, NFE2, and HOXC8 may be involved in tumor immune regulation and affect immunotherapy." (PMID 36650426, 2023). "Similarly, regarding tumour metastasis, we found that knockdown of HOXC8 greatly decreased the metastatic area of tumours in the liver compared to the control group, while overexpression of HOXC-AS3 increased the metastatic area." (PMID 35387975, 2022). "Therefore, we conclude that HOXC-AS3 promotes NSCLC tumour growth and metastasis in vivo by increasing HOXC8 expression." (PMID 35387975, 2022). "In these cancers HOXC8 has been reported to act either as tumour suppressor gene or oncogene, suggesting that the function of HOXC8 may depend on the activation or repression of different HOXC8 targets whose expression can be tissue-specific." (PMID 28202042, 2017). "Forced CDH11 expression in HOXC8-knockdown cells did little on the rate of tumor outgrowth." (PMID 24810778, 2014). "Based on the connection between HOXC8 and ON, it could be speculated that wound formation (including certain aspects of tumour formation) could be a trigger." (PMID 21712827, 2011). "However, a classical tumour suppressor requires the continued presence of its gene product and this property lacks HOXC8, since in normal tissues, HOXC8 is expressed at basal levels only." (PMID 21712827, 2011). "The transcription factor HOXC8 regulates many genes involved in tumour progression." (PMID 21712827, 2011). "Similarly, tumour samples from patients that were characterised as nodal positive (N1) harboured significantly less Hoxc8 mRNA copies than samples from N0 patients." (PMID 21712827, 2011). "The results showed faster tumor growth and heavier tumors in the overexpression group compared to the vector group, whereas the increased volume and could be counteracted by further treatment with an shRNA-lentiviral plasmid targeting HOXC8." (PMID 38641828, 2024).
tumor (continued). "Mechanically, circSLCO1B3 not only promoted ICC proliferation and metastasis via miR-502-5p/HOXC8/SMAD3 axis, but also eradicated anti-tumor immunity via suppressing ubiquitin-proteasome-dependent degradation of PD-L1 by E3 ubiquitin ligase SPOP." (PMID 38641828, 2024). "Among them, HOXC11, HOXC10, HOXC8, and HOXC12 interact with HOTAIR in gastrointestinal tumors to jointly promote tumor formation and development." (PMID 36924407, 2023). "We also found that ARL4C and HOXC8 were upregulated, and FABP4, PCOLCE2, SERPING1, and SRPX were downregulated in tumor tissue compared to corresponding healthy tissue." (PMID 35664768, 2022). "Among these genes, six (HOXA6, STC2, HSD17B8, TFAP2A, CYP1B1, and HOXC8) were reported to be osteogenesis-/chondrogenesis-related genes, and five (ADRA1A, TSPYL5, TES, TNFRSF10D, and MBP) were reported to be tumor-suppressor genes." (PMID 31889115, 2019). "HOXC8 expression had significantly positive correlation with TNM stage (P = 0.0378), higher tumor size (P = 0.0212) and positive nodal status (P = 0.0217), suggesting an important association between HOXC8 upregulation and tumor proliferation and metastasis." (PMID 29367650, 2018). "Our array data showed HOXC8 downregulation in CSC compared to normal MaSC, suggesting a possible role as tumour suppressor gene that regulates normal function of mammary stem cells." (PMID 28202042, 2017). "Among the differentially expressed genes identified in this study, HOXC8 was found consistently downregulated in CSC and therefore represented a novel putative tumour suppressor candidate." (PMID 28202042, 2017). "Although the exact role of HOXC8 in tumorigenesis remains to be fully elucidated, the ability of HOXC8 to regulate the expression of genes essential for cell adhesion, migration and tumorigenesis indicates that it may impact tumor development by facilitating events toward tumor metastasis." (PMID 24810778, 2014). "The Hoxc8 mRNA levels in diseased human pancreas tissues were significantly increased over normal in PDAC, but negatively related to tumour stage (P=0.09)." (PMID 21712827, 2011). "HOXC8 not only affects the progression and prognosis of CRC by mediating the upregulation of tumor escape-related pathways such as EMT, but it may also be involved in immune regulation within the TME." (PMID 39980564, 2025). "Moreover, HOXC8, HOXD10, and HOXD11 were confirmed to be involved in biological processes related to tumor formation and progression, such as clone formation and cell metastasis." (PMID 36718148, 2023). "Elevated expression of HOXC-AS3/YBX1/HOXC8 occurs in NSCLC cells, and inhibition of their expression significantly suppresses cancer cell proliferation, migration and invasion, resulting in attenuated tumour growth and metastasis in vivo." (PMID 35387975, 2022). "The Hoxc8 mRNA levels in diseased human pancreas tissues were significantly increased over normal in PDAC and autoimmune chronic pancreatitis specimens (P<0.01, respectively), but negatively related to tumour stage (P=0.09)." (PMID 21712827, 2011). "Moreover, HOXC8 facilitated NAT10 transcription in CCa cells by binding to its promoter region, which facilitated the proliferation, migration and invasion of CCa cells in vitro and tumor progression in vivo." (PMID 37818745, 2023). "As we previously reported, silencing HOXC8 exhibited no obvious effect on in vivo tumor outgrowth." (PMID 24810778, 2014).
cancer (29 papers, 2011 to 2025). A tumor composed of atypical neoplastic, often pleomorphic cells that invade other tissues. "HOXC8 is a potential driver gene for many cancer cells and is associated with cell proliferation, adhesion, migration, and metabolism-related processes and can be considered as a global regulator of growth and differentiation." (PMID 36479313, 2022). "Dysfunction of HOXC8 is implicated in various cancers, including breast, prostate, cervical and pancreatic cancers, by facilitating cell migration and metastasis." (PMID 29296180, 2017). "Grading of primary carcinomas was negatively associated with the extent and intensity of HOXC8 staining (P=0.03)." (PMID 21712827, 2011). "Furthermore, TCGA analysis showed significant upregulation of HOXC8 mRNA expression in CCa (P<0.05), which was positively associated with cancer stage and lymph node metastasis (P<0.05)." (PMID 37818745, 2023). "Recent studies have also linked HOXC8 into the tumorigenesis of various cancer types." (PMID 24810778, 2014). "Furthermore, grading of primary carcinomas was negatively associated with the extent and intensity of HOXC8 staining." (PMID 21712827, 2011). "Furthermore, grading of primary carcinomas was negatively associated with HOXC8 staining (P=0.03)." (PMID 21712827, 2011). "It would be of great interest to systematically analyze HOXC8 expression in various cancer types to better ascertain the role of HOXC8 in tumorigenesis." (PMID 40701951, 2025). "YBX1 is a well-established transcription factor that has been reported to induce the transcription of oncogenic genes, such as FOXA1, FZD7, and HOXC8 in cancers." (PMID 38491348, 2024). "We next evaluated the mRNA levels of HOXC8 in multiple cancer types using TNMplot, which showed that HOXC8 was upregulated in many cancer types, including STAD." (PMID 37670969, 2023). "It has been reported that HOXA9 and HOXC8 are involved in glycolysis and play important role in cancer metabolism." (PMID 31013831, 2019). "As a transcription factor, HOXC8 is able to regulate and coordinate multiplevital genes (e.g. Mgl1, Embigin, Meis1, and Fyn) involved in cancer development and progression." (PMID 32922885, 2018). "Massive evidence supports that HOXC8 plays an important role in malignant tumor formation and progression." (PMID 32922885, 2018). "We found that HOXC8 shRNA knockdown resulted in significant reduction of migratory cells, and ecto-expression of HOXC8 significantly increased the migration of cancer cells." (PMID 29367650, 2018). "The high HOXC8 expression rate (78.9%) was significantly higher in cancer specimens compared to normal lung tissues (16.7%)." (PMID 29367650, 2018). "As a member of HOX family, HOXC8 has been found to be deregulated in multiple cancers including breast, colon, cervical, prostate and ovarian cancers, and functions as a transcription activator or repressor to regulate a number of genes transcription." (PMID 29367650, 2018). "Functional studies demonstrated that HOXC8 gain of function induces a decrease in the CD44+/CD24-/low cancer stem cell population and proportion of chemoresistant cells, with a concomitant increase in CD24+ differentiated cells." (PMID 28202042, 2017). "We next assessed the functional role of HOXC8 in breast CSC by inducing its expression in cancer cell lines." (PMID 28202042, 2017). "Increased HOXC8 levels also decrease the ability of cancer cells to form mammospheres and to grow in anchorage-independent conditions." (PMID 28202042, 2017). "It has been described by others and us that HOXC8 knockdown is associated with increased expression of OPN, which in turn stimulates the proliferation of cancer cells via two different pathways." (PMID 21712827, 2011). "In addition to its well established developmental role, dysregulated HOXC8 expression has been observed in various cancer types." (PMID 40701951, 2025). "Dysregulated HOXC8 expression has been reported in a variety of cancer types." (PMID 40701951, 2025).
cancer (continued). "In addition, homeobox (HOX) genes such as HOXB7, HOXC8, and HOXB13, which are used as PC diagnostic markers, are involved in malignant cell transformation and/or cancer progression." (PMID 36428807, 2022). "In fact, the role of HOXC8 has been deciphered in other types of cancers." (PMID 35111675, 2021). "Moreover, HOXC8 was found to be upregulated in cervical cancer, prostate cancer and colorectal cancer and facilitated the migration and metastasis of cancer cells." (PMID 29367650, 2018). "Notably, the expression difference between cancer specimens and normal tissues are statistically significant for HOXC8 (P < 0.0001)." (PMID 29367650, 2018). "Therefore, HOXC8 as a potential oncogenic driver, plays an important role in cancer cell proliferation, migration and invasion, by overregulating many oncogenes and downregulating tumor suppressor genes." (PMID 32922885, 2018). "Of the genes that were altered in all cancer subtypes, the expression of five matched all datasets (HOXC8, HOXC11, HOXD8, PROX1, SIX2), although the overlap was found when considering the expression in the majority of the subtypes as HOXC11 and PROX1 were downregulated in TN CSC." (PMID 28202042, 2017). "HOXC8 protein expression was found to be deregulated in various cancers." (PMID 26090721, 2015). "Although it remains unclear how HOXC8 takes part in cancer process, HOXC8 must act as a transcription factor to regulate its target genes that participate in biological processes." (PMID 26090721, 2015). "To have a systemic view of HOXC8 expression in various cancer types, we utilized eBioPortal to compare the level of HOXC8 mRNA across 30 cancer categories using dataset from Pan-cancer analysis of whole genomes and found that the level of HOXC8 mRNA was high in 8 cancer categories." (PMID 40701951, 2025). "In fact, HOXC8 could be targeted by several miRNAs in the cancer studies." (PMID 35111675, 2021). "Thus, sustained expression of HOXA9 and HOXC8 may provide a potential therapeutic strategy to inhibit tumor growth in glycolysis-exuberant cancer." (PMID 31013831, 2019). "However, low mRNA levels of CDH11, ILF3 or HOXC8 were evident in cancer stage 0." (PMID 29296180, 2017). "Several targets of HOXC8 have been characterised and their functional role in the context of HOXC8 regulation may provide new insights into the role of HOXC8 in different cancer types." (PMID 28202042, 2017). "Furthermore, loss of HOXC8 in non-tumorigenic mammary epithelial cells expands the cancer stem/progenitor cells pool, increases stem cell self-renewal, prevents differentiation induced by retinoic acid and induces a transformed phenotype." (PMID 28202042, 2017). "Furthermore, HOXC8 seems to have an essential role in cancer development and progression." (PMID 21712827, 2011). "The results revealed that HOXC8 was upregulated in AZ521 and HR cancer cell lines compared with that in a TGCH cell line." (PMID 37670969, 2023). "Elevated YBX1 expression increased the transcription of HOXC8, as YBX1 bound to its promoter, leading to enhanced cancer cell proliferation, migration and invasion." (PMID 35387975, 2022). "The transcription factor Homeobox C8 (HOXC8) is overexpressed and regulates many important genes involved in the proliferation and invasion of many malignant tumors." (PMID 32922885, 2018). "Gain of function of HOXC8 reduced CSC self-renewal and the ability of cancer cells to grow in anchorage-independent conditions." (PMID 28202042, 2017). "qPCR analysis of a number of reported miR196a targets in other cancers, KRT5, ANXA1, S100A9 and HOXC8, was conducted." (PMID 25860510, 2015). "We found two major types of complexes that are affected by miRNAs during cancer progression; the first contains SMAD3, SMAD2, SMAD4, SMAD6, FOXO1, HOXC8, and SKIL, which are connected to AKT1, which is in turn a key modulator of TGF-B signaling pathway." (PMID 24391925, 2013).